RIC8A (RIC8 guanine nucleotide exchange factor A)
Description:
Chaperone that specifically binds and folds nascent G alpha proteins prior to G protein heterotrimer formation, promoting their stability and activity: folds GNAI1, GNAO1, GNA13 and GNAQ (By similarity). Does not fold G(s) G-alpha proteins GNAS nor GNAL (By similarity). Also acts as a guanine nucleotide exchange factor (GEF) for G alpha proteins by stimulating exchange of bound GDP for free GTP (By similarity). Involved in regulation of microtubule pulling forces during mitotic movement of chromosomes by stimulating G(i)-alpha protein (GNAI1), possibly leading to release G(i)-alpha-GTP and NuMA proteins from the NuMA-GPSM2-G(i)-alpha-GDP complex (By similarity). Also acts as an activator for G(q)-alpha (GNAQ) protein by enhancing the G(q)-coupled receptor-mediated ERK activation.
Synonyms: synembryn; synembryn-A; RIC8
Tractability: Antibody: its Gene Ontology location is reachable by antibodies, with medium confidence; the Human Protein Atlas places it where antibodies can reach. PROTAC: ubiquitination databases record sites on it; its protein half-life has been measured.
Gene: Protein-coding gene on chromosome 11 (207,499 to 215,113, forward strand). Ensembl gene ENSG00000177963.
Subcellular location: Cytoplasm, cell cortex; Cytoplasm
Subcellular location (Human Protein Atlas): Cytosol; Plasma membrane
Gene Ontology:
Molecular function: protein binding; G-protein alpha-subunit binding; guanyl-nucleotide exchange factor activity; protein folding chaperone; GTPase activator activity
Biological process: G protein-coupled receptor signaling pathway; protein folding
Cellular component: cytoplasm; plasma membrane; cell cortex; membrane
Genetic constraint (gnomAD): Loss-of-function variants: 37 observed, 48.4 expected, observed/expected ratio (o/e) 0.76, 90% interval 0.59 to 1.01. The upper end of that interval is the gene's LOEUF score, 1.01, which puts it in group 4 of 6, group 1 being the genes least tolerant of losing a copy. Missense variants: 679 observed, 717.79 expected, observed/expected ratio (o/e) 0.95, 90% interval 0.89 to 1.01. Synonymous variants: 287 observed, 292.81 expected, observed/expected ratio (o/e) 0.98, 90% interval 0.89 to 1.08.
Homologues: Orthologues: chimpanzee RIC8A (99% identical), macaque RIC8A (98% identical), dog RIC8A (89% identical), pig RIC8A (89% identical), mouse Ric8a (88% identical), rat Ric8a (87% identical), guinea pig RIC8A (82% identical), rabbit RIC8A (81% identical), zebrafish ric8a (59% identical), Drosophila melanogaster ric8a (33% identical), Caenorhabditis elegans ric-8 (26% identical). Paralogues in human: RIC8B (49% identical).
Diseases named in the same sentence as RIC8A in open-access papers:
RIC8A is named in the same sentence as 20 diseases in open-access papers, as found by Europe PMC text mining. Sharing a sentence is not in itself a finding about the gene and the disease. The quoted sentences say what the papers report.
breast carcinoma (6 papers, 2009 to 2024). "Together with the presence of the truncating mutation, this suggests a specific importance of the RIC8A gene in a subset of breast cancers." (PMID 19432969, 2009). "Here, this strategy led to the identification of RIC8A as a gene undergoing deletional and mutational inactivation in a breast cancer cell line, as well as in vivo evidence of loss of its expression in a subgroup of aggressive breast cancers." (PMID 19432969, 2009). "This integrated genomic approach led to the identification of RIC8A at 11p15 as a putative candidate target gene for the genomic deletion in the ZR-75-1 breast cancer cell line." (PMID 19432969, 2009). "Using integration of unbiased genome-wide data from these two technologies, we describe here the identification of a putative target gene, RIC8A, located in a frequently deleted region at 11p15 in breast cancer." (PMID 19432969, 2009). "While RIC8A is located in one of the most frequently deleted regions in breast cancer, the deletion obviously involves a large number of genes." (PMID 19432969, 2009). "To examine the importance of RIC8A as a target gene for the frequent deletion in chromosome band 11p15 in breast cancer, we analyzed the expression of RIC8A in previously published breast cancer microarray data sets." (PMID 19432969, 2009). "RIC8A was flagged as a candidate for undergoing NMD in the breast cancer cell line ZR-75-1." (PMID 19432969, 2009).
uveal melanoma (3 papers, 2016 to 2025). A melanoma derived from melanocytes of the uveal tract. "Overall, these results collectively demonstrate two future possibilities to amerliorate GNAQ/11-induced uveal melanoma; reduction of Gαq/11-Q209L driver oncoprotein levels through Ric-8A inhibition or phorbol ester treatment." (PMID 27348266, 2016). "The present study provides a genetic demonstration that melanocyte deletion of the molecular chaperone Ric-8A suppressed tumorigenesis mediated by the uveal melanoma oncogenic driver G protein, Gαq-Q209L." (PMID 27348266, 2016). "In diseases driven by CA αq mutants, such as uveal melanoma, we can speculate that inhibition of Ric-8A function could allow for more effective inhibition of mutant αq by YM." (PMID 40118458, 2025). "To extend this analysis further and to orthogonally computationally validate CDS2, RIC8A and SPTSSA, and to identify further candidates, including nonparalog genes, we adopted an additional approach to identify gene vulnerabilities that were specific to uveal melanoma." (PMID 40615675, 2025).
melanoma (2 papers, 2016 to 2019). A malignant, usually aggressive tumor composed of atypical, neoplastic melanocytes. "Ric-8A gene deletion significantly suppressed tumorigenesis in a mouse model of oncogenic Gαq-driven melanoma, implying its regulation of YAP signaling pathway." (PMID 31741433, 2019). "In fact, Ric-8A deletion imparted a modest in vitro growth advantage to cultured melanocytes and melanoma cell lines." (PMID 27348266, 2016). "The melanoma cell lines were pre-treated with 4OHT ex vivo to induce Ric-8A knockout before secondary graft experiments." (PMID 27348266, 2016). "Here, using mouse melanocyte cell graft tumorigenesis models, we determined that Ric-8A genetic ablation attenuated the abundance and melanoma-driving potential of Gαq-Q209L." (PMID 27348266, 2016). "Ric-8A deletion completely blocked melanoma tumorigenesis of the grafted GNAQQ209L melanocyte cell line and secondarily-derived GNAQQ209L melanoma cell lines." (PMID 27348266, 2016). "Ric-8AFlox/Flox; GNAQQ209L murine melanoma cell lines were cultured ex vivo from primary tumor explants and secondary tumor formation from these cells was also blocked by in vitro Ric-8A deletion." (PMID 27348266, 2016). "Our ongoing and future work involves active trials to reduce Gαq/11-Q209L oncoproteins through Ric-8A inhibition or phorbol ester inhibitory feedback as two new potential strategies to treat GNAQ/11Q209L melanoma." (PMID 27348266, 2016). "Ric-8A knockout dramatically blunted Gαq-Q209L-driven secondary melanoma tumor progression." (PMID 27348266, 2016). "Here, we conducted a proof-of-concept investigation demonstrating that genetic ablation of Ric-8A blocked GNAQQ209L-driven melanocyte transformation and melanoma pathogenesis using cell graft mouse tumor models." (PMID 27348266, 2016).
osteoarthritis (2 papers, 2022 to 2025). A noninflammatory degenerative joint disease occurring chiefly in older persons, characterized by degeneration of the articular cartilage, hypertrophy of bone at the margins and changes in the synovial membrane. "In osteoarthritis tissues, circPDE4B is used as a scaffold to promote the association between RIC8A and MID1 by promoting RIC8A degradation via proteasomal degradation." (PMID 36506086, 2022). "On the other hand, Mid-1 ubiquitinates RIC8 guanine nucleotide exchange factor A, which promotes the progression of osteoarthritis by activating p38 mitogen-activated protein kinase signaling pathway in chondrocytes, thus pointing to a protective effect of Mid-1 signaling in OA." (PMID 40443734, 2025).
Anxiety (1 paper, 2013). Intense feelings of nervousness, tension, or panic often arise in response to interpersonal stresses. "Moreover, Ric8a haploinsufficiency results in behavioural abnormalities, such as increased anxiety-like behaviour and impaired spatial memory as demonstrated in heterozygous Ric8a+/- mice." (PMID 23977396, 2013).
breast tumours (1 paper, 2009). "However, analysis of gene expression data from breast tumours identified a small group of aggressive tumours that displayed low levels of RIC8A transcripts." (PMID 19432969, 2009).
Encephalopathy (1 paper, 2024). Encephalopathy is a term that means brain disease, damage, or malfunction. "Here, through a massive characterization of GNAO1 mutations, we uncovered a neomorphic feature shared by all Gαo encephalopathy mutants: a strong gain of interaction with Ric8A and, even more surprisingly, with Ric8B." (PMID 38874642, 2024).
invasive breast carcinoma (1 paper, 2009). A carcinoma that infiltrates the breast parenchyma. "Exhaustive pyrosequencing of the entire RIC8A promoter region in early invasive breast cancers as well as in pre-invasive tumours (DCIS) and locally advanced (T3/T4) tumours excluded also promoter hypermethylation as a mechanism for RIC8A gene silencing." (PMID 19432969, 2009).
Lissencephaly (1 paper, 2024). A spectrum of malformations of cortical development caused by insufficient neuronal migration that subsumes the terms agyria, pachygyria and subcortical band heterotopia. "However, unlike in classic models of cobblestone lissencephaly, these phenotypes resulted not from Ric8a deficiency in brain neural cell types, but from deficiency in microglia." (PMID 39635981, 2024). "However, unlike classic models of cobblestone lissencephaly, where radial glial fibers typically retract, radial glial fibers in ric8a mutants instead extended beyond the breaches." (PMID 39635981, 2024).
lung carcinoma (1 paper, 2019). "Collectively, these results suggest that loss of RIC8A synergizes with EGFR inhibition by attenuating YAP signaling in lung cancer." (PMID 31741433, 2019). "Therefore, targeting RIC8A might be promising to prevent EGFR TKI resistance in lung cancer." (PMID 31741433, 2019).
pulmonary TB (1 paper, 2016). "In this study, RIC8A was down-regulated in pulmonary TB, suggesting that RIC8A may be associated with the pulmonary TB development through regulating MAP kinase signaling pathway with G proteins." (PMID 27655333, 2016).
cancer (5 papers, 2009 to 2024). A tumor composed of atypical neoplastic, often pleomorphic cells that invade other tissues. "We have also discovered that previously reported mutations in RIC8A, which are enriched in metastatic breast cancer, specifically, are enriched in the HR-deficient cancers." (PMID 39198848, 2024). "For example, this region harbours the SIRT3 gene, which has been associated with cancer and whose expression showed correlation with copy number loss together with RIC8A." (PMID 19432969, 2009). "Targeting Ric-8A serves as a rational, yet unexplored approach to reduce the functional abundance of oncogenic Gαq/11 in order to blunt cancer signaling." (PMID 27348266, 2016). "Even in the absence of consistent trends in various transformed tissues, these data suggest that altered Ric-8A protein expression is a frequent event during cancer development." (PMID 24466196, 2014). "To better understand the functional role of Ric-8A in cell division, we employed HeLa cells as an in vitro carcinoma cell line model." (PMID 24466196, 2014). "This point to the possibility that RIC8A would play a role in cancer relevant pathways and that its inactivation could be important to the pathogenesis of the disease." (PMID 19432969, 2009). "The mRNA of STATH, RIC8A, and ABCC5 levels were downregulated in cancer samples in comparison to the control samples." (PMID 35992817, 2022). "We then examined Ric-8A expression in various cancers compared to normal tissues using a tumor array in which tissue lysates from cancer biopsies or from corresponding non-tumor tissues (age- and sex- matched) were spotted." (PMID 24466196, 2014).
tumor (4 papers, 2009 to 2025). "This indicates that the modest in vitro melanocyte proliferation advantage conferred by Ric-8A knockout was negated by loss of Gαq-Q209L oncoprotein folding capacity during in vivo tumor growth." (PMID 27348266, 2016). "Ric-8A deletion substantially attenuated GNAQQ209L-driven tumor progression and measured tumor weights at the completion of the experiments." (PMID 27348266, 2016). "Both tumor cell lines retained the capacity to induce Ric-8A deletion and deplete endogenous G proteins and Gαq-Q209L." (PMID 27348266, 2016). "During the screening of the tumor array, we noted high Ric-8A protein levels in normal testis, a site of rapid cell proliferation." (PMID 24466196, 2014). "In the same tumours, genes in this region, including RIC8A, were shown to be statistically significantly deleted and underexpressed when combining copy number and gene expression data." (PMID 19432969, 2009). "On the other hand, if Ric-8A inhibition could be directed to tumor cells, the effect on endogenous G proteins may provide added therapeutic efficacy of tumor inhibition." (PMID 27348266, 2016). "Deletion of Ric-8A in culture before GNAQQ209L cell grafting completely abrogated tumor growth." (PMID 27348266, 2016). "Finally, tumorigenesis initiated from GNAQQ209L cell grafts, followed by host mouse systemic tamoxifen treatment to delete Ric-8A in the grafted cells completely abrogated GNAQQ209L-driven tumor progression unless a stable human RIC-8A transgene was used to rescue the floxed Ric-8A alleles." (PMID 27348266, 2016). "Specifically, we found a low positive correlation between APLN and CYR61 (r = 0.16), a stronger correlation between APLNR and CYR61 (r = 0.68), a low correlation between APLNR and RIC8A (r = 0.20), and a moderate correlation between APLNR and TUBA1A (r = 0.58) in tumor patients." (PMID 39962271, 2025).
neurodevelopmental disorder (2 papers, 2022 to 2023). A behavioral and cognitive disorder with onset during the developmental period that involves impaired or aberrant development of intellectual, motor, or social functions. "In summary, we have taken a step toward establishing the inhibition of the NCS-1/Ric8a complex as a treatment for FXS or other neurodevelopmental disorders associated with synaptic homeostasis dysfunction." (PMID 36466176, 2022). "In neurodevelopmental disorders, where synapse number is abnormally high, the inhibition of the NCS-1/Ric-8A complex formation reduces synapse number and improves learning in Fragile X syndrome animal models." (PMID 38018500, 2023). "Neuronal calcium sensor 1 (NCS-1), through its interaction with the guanine-exchange factor Ric8a, regulates the number of synapses and the probability of the release of a neurotransmitter, the two neuronal features that are altered in FXS and other neurodevelopmental disorders." (PMID 36466176, 2022).
infection (1 paper, 2016). The state of being infected such as from the introduction of a foreign agent such as serum, vaccine, antigenic substance or organism. "Ric-8A deletion in the melanocyte cell line mediated by Cre-NLS lentiviral infection or by 4-hydroxytamoxifen (4OHT) activation of Cre recombinase, decreased Ric-8A abundance and caused concomitant decreases in the levels of G protein subunits folded by Ric-8A." (PMID 27348266, 2016).
nervous system disorder (1 paper, 2023). A non-neoplastic or neoplastic disorder that affects the brain, spinal cord, or peripheral nerves. "Given the interest in the NCS-1/Ric-8A complex as a therapeutic target in nervous system disorders, it is necessary to shed light on this molecular mechanism of action at atomic level." (PMID 38018500, 2023).
RIC8A also shares sentences with these, for which no sentence is quoted: colon cancer (1 paper); latent infection (1); neurodegenerative disease (1); ovarian carcinoma (1).